GTPBP6 (GTP binding protein 6)
Synonyms: PGPL; FLJ20977
Tractability: Small molecule: a structure with a bound ligand is known. PROTAC: ubiquitination databases record sites on it; its protein half-life has been measured.
Gene: Protein-coding gene on chromosome X (303,346 to 318,846, reverse strand). Ensembl gene ENSG00000178605.
Subcellular location (Human Protein Atlas): Mitochondria; Nucleoplasm
Gene Ontology:
Molecular function: ribosomal large subunit binding; GTP binding; ribosome binding
Biological process: mitochondrial large ribosomal subunit assembly
Cellular component: mitochondrion; cytoplasm
Homologues: Orthologues: chimpanzee GTPBP6 (99% identical), dog GTPBP6 (76% identical), rabbit GTPBP6 (72% identical), macaque GTPBP6 (63% identical), mouse Gtpbp6 (62% identical), rat Gtpbp6 (60% identical), tropical clawed frog gtpbp6 (59% identical), zebrafish gtpbp6 (55% identical), Drosophila melanogaster CG5116 (38% identical).
Diseases named in the same sentence as GTPBP6 in open-access papers:
GTPBP6 is named in the same sentence as 5 diseases in open-access papers, as found by Europe PMC text mining. Sharing a sentence is not in itself a finding about the gene and the disease. The quoted sentences say what the papers report.
Klinefelter syndrome (2 papers, 2020 to 2021). A sex chromosome disorder caused by the presence of an extra X chromosome in the male karyotype. "In contrast, human GTPBP6 is probably expressed constitutively in all tissues and its expression must be tightly controlled, as abnormally high GTPBP6 levels in lymphoblasts have been associated with language impairment in men with Klinefelter's syndrome." (PMID 33264405, 2020).
Alzheimer disease (1 paper, 2021). A progressive, neurodegenerative disease characterized by loss of function and death of nerve cells in several areas of the brain leading to loss of cognitive function such as memory and language. "Therefore, we speculate that MTUS2, GTPBP6, TIAM-1 and SHROOM2 are likely associated with Alzheimer’s disease." (PMID 33525573, 2021).
cognitive deficits (1 paper, 2025). "GTPBP6 expression, for instance, negatively correlates with IQ, especially in individuals with random XCI patterns, while skewed XCI patterns result in milder cognitive deficits." (PMID 40018421, 2025). "Normally, XCI balances gene dosage, but in KS, genes such as GTPBP6 (guanosine triphosphate binding protein 6), EIF2S3 (eukaryotic translation initiation factor 2 subunit 3), and KDM5C (Lysine(K)‐specific demethylase 5C) escape inactivation and are overexpressed, contributing to cognitive deficits." (PMID 40018421, 2025).
GTPBP6 also shares sentences with these, for which no sentence is quoted: dyschondrosteosis (1 paper); mitral valve prolapse (1).